CD44 (CD44 molecule (IN blood group))
Diseases named in the same sentence as CD44 in open-access papers (continued):
Sharing a sentence is not in itself a finding about the gene and the disease.
breast carcinoma (continued). "We performed qRT-PCR for the major stemness-related transcription factors, such as NANOG, SOX2, OCT4 and BMI1, as well as the marker CD44, a panel that predicts a transcriptional shift to a stem-like state in breast cancer cells." (PMID 35195687, 2022). "In another clinical trial, advanced breast cancer patients with a GSI MK-0752 treatment plus docetaxel have shown decreased CD44+CD24− and ALDH+ BCSC populations and lower mammosphere formation from their biopsies (NCT00106145, NCT00645333)." (PMID 35805056, 2022). "We compared the PTEN, pAkt, and CD44/CD24 protein levels in breast cancer tissue determined by IHC with the serum levels of PD-L1." (PMID 35053979, 2022). "Contradictory results have been reported regarding the status of KYNU in breast cancers, depicting it either as a tumor suppressor gene or placing the enzyme downstream of the CD44-NF-κB signaling axis to promote breast cancer cell metastasis." (PMID 35681770, 2022). "In the current study, we found that metastatic lymph nodes showed higher expression of CD44 compared to primary tumors in tissue samples collected from breast cancer patients." (PMID 36289750, 2022). "A study showed that endothelial cells co-cultured with breast cancer cells enriched the CD44 high CD24 low stem cell population in breast cancer cells." (PMID 36550571, 2022). "In breast cancer tumor cells, raft localization of palmitoylated CD44 is considered to prohibit cell migration." (PMID 35733341, 2022). "NGF stimulates the invasion of breast cancer MDA-MB-231 cells as a result of the binding of CD44 with the TrkA receptor and the activation of the p115RhoGEF/RhoA/ROCK1 cascade." (PMID 35956937, 2022). "To date, successful studies have been performed with respect to the detection of the biomarker of breast cancer, as well as the common biomarker of cancer stem cell protein coding gene CD44." (PMID 36421133, 2022). "We also found morphological changes in breast cancer cells after the knockdown and overexpression of CD44." (PMID 36289750, 2022). "Our study showed that, when cultured in RGD-containing HAGM cryogels, the RGD peptide interfered with the cellular behavior of 4T1, a CD44-positive metastatic breast cancer cell line." (PMID 35198956, 2022). "The atypical tumor-suppressing proteins interacted with CD44, a breast cancer stem-cell marker, and these interactions drove the elimination of CD44-positive tumor cells." (PMID 34976221, 2022). "Through targeting Bcl-2, CD44, and SIRT1 (silent information regulator 1), Rac1, Fra-1, Notch-1, and different cyclins, exogenous expression of miR-34a in breast cancer cells caused cell death and decreased cell proliferation and migration." (PMID 36325275, 2022). "To meet this goal, we have developed HA-decorated niosomal nanoparticles as a potential platform for targeted delivery of epirubicin to breast cancer cells, especially CD44-overexpressing cell lines." (PMID 35875198, 2022). "Another study investigating the treatment of CD44- expressing breast cancer cells prepared a combination of HA, chitosan and lipoic acid NPs." (PMID 35645591, 2022). "In order to analyze the CD44-positive cell population in primary tumors and lymph nodes, tissue samples were collected from 14 breast cancer patients." (PMID 36289750, 2022). "For example, a population of cells expressing CD44 high/CD24 low was identified as CSCs in breast cancer." (PMID 35464064, 2022). "Zerumbone, a sesquiterpenoid and cyclic ketone, suppressed EGF-dependent CD44 expression through inhibition of the STAT3 pathway in breast cancer cell lines (SKBR3 and MDA-MB468)." (PMID 35785191, 2022). "For the first time, we have found that CD44 regulates FOXA2 localization through AKT to promote the metastatic ability of breast cancer cells." (PMID 36289750, 2022).
breast carcinoma (continued). "For instance, primary tumours from breast cancer patients with high CD44+CD24− correlated with the presence of distant metastasis, including bone and pleural metastasis, as well as show early bone marrow disseminated cancer cells." (PMID 35326385, 2022). "High expression levels of adhesion receptor CD44, which binds hyaluronan with high affinity, has been observed and shown to promote collective invasion in breast cancer." (PMID 35574334, 2022). "Its expression strongly correlated with P-PKM2 Tyr105 levels in breast cancer cells; P-PKM2 Tyr105 induced translocation of transcription regulator YAP (YES associated protein) to the nucleus, thereby enhancing CD44 expression." (PMID 35054968, 2022). "In 2015, Kim and co-workers reported that 1 exhibited anticancer activity against breast cancer stem-like cells by reducing the expression of CD44, Oct4, Notch2, β-catenin and Sox2 proteins." (PMID 35209235, 2022). "Due to the metastatic cancerous nature of CD44, it is a key biomarker for early diagnosis of breast cancer." (PMID 36354475, 2022). "Xenograft initiating CD44+CD49fhighCD133/2 high cells display self-renewal in vivo and greater tumorigenicity in ER− breast cancer." (PMID 35392236, 2022). "The results using 4T1.2 mammary tumor cells showed that Eno1 pulled down both WT and MT CD44 proteins, indicating that extracellular Eno1 interacted with the ECM domain of CD44." (PMID 35547745, 2022). "It was shown that ESRP1 promotes lung cancer metastasis by regulating CD44 splicing in ER-negative 4T1 mouse mammary tumor cells." (PMID 36052258, 2022). "The expression of CD44 in breast cancer cells can be upregulated through the activation of different EMT-related transcription factors including SNAI1 and SLUG." (PMID 33506060, 2021). "Uchiumi’s study found that the ER+ breast cancer cells express higher populations of CD44+/CD24−, revealing the high level of CSCs retaining ability." (PMID 34098945, 2021). "Forkhead box protein 3 (Foxp3) bound to the CD44 promoter and significantly inhibited its expression, suppressing the invasion and metastatic capabilities of human breast cancer cells." (PMID 34944493, 2021). "This phenomenon was also seen in breast cancers, where tumors were found to be enriched for the CD44+/CD24– CSC subpopulation following exposure to radiation." (PMID 33681228, 2021). "Studies have identified CD44+CD24− in breast cancer; CD44+CD24+EpCAM+ in pancreatic or ovarian cancer; and a high expression of neuron stem markers, such as CD133, CD44, and Nestin, and transcript factors, such as SOX2 and OCT4, in GBM." (PMID 34069945, 2021). "Many molecular markers of stemness have been identified in various cancer types, such as CD44 in breast cancer 2 and LGR5 in colon cancer 17-21." (PMID 33995681, 2021). "Investigation of breast cancer patients with the metastatic disease showed a considerably increased level of serum CD44." (PMID 34599251, 2021). "Radiation-induced EMT and stemness phenotype were identified using breast cancer stem cells (CSCs) marker (CD24−/low/CD44+) and mammosphere formation assay." (PMID 34217266, 2021). "Specific CD44 isoforms have been identified as potential targets for anti-cancer therapies: early studies are investigating the potential for therapeutic targeting of CD44+ CSCs in breast cancer." (PMID 33628765, 2021). "Cancer stem cell model and a discovery of CD44 as a marker of tumor initiating breast cancer cells further extended attractiveness of CD44." (PMID 34257584, 2021). "MCF-7 cells were used to generate CD44+/CD24− breast cancer stem cell (BCSC)-enriched mammospheres following previously reported methods." (PMID 33919234, 2021). "A study of CD44 in breast cancer patients reported a direct correlation between serum CD44 level and breast cancer occurrence." (PMID 34599251, 2021).
breast carcinoma (continued). "In another study, the frequency of the CD44+/CD24- population—marking breast cancer stem cells (CSCs)—was diminished, and the expression and activation of the pro-inflammatory IL-6/STAT3 pathway reduced after Sdc-1 siRNA knockdown." (PMID 34070901, 2021). "A TGF-βR2 inhibitor (LY2109761) was then used to inhibit ALG2 overexpressing breast cancer cell lines which induced apoptosis post-radiotherapy and diminished tumorsphere formation as well as CD44+/CD24− CSCs." (PMID 34680503, 2021). "Remarkably, CD44 and PrPC are co-expressed and co-localize on the cell membrane in human breast cancer cell line MCF7/Adr." (PMID 33418999, 2021). "In this study, we analysed the effect of the same compound treatment in MDA-MB-231 TNBC upon CD15s and CD44 expression in different breast cancer subpopulations." (PMID 34206154, 2021). "In particular, DBD-CAP markedly down-regulated CD44, which is the major cellular receptor of the extracellular heteropolysaccharide hyaluronan, in both ER+ and ER- breast cancer cells." (PMID 35111687, 2021). "Another study in breast cancer showed that co-culturing MSCs with tumor cells enriches for the CD44+/CD24− CSC population." (PMID 33530455, 2021). "Because TNBC is the most aggressive type of breast cancer, the spontaneous conversion of CD44-/CD24- TNBC cells into CD44+/CD24- CSCs was further tested in TNBC cell lines." (PMID 34318746, 2021). "Breast cancer was the first human solid tumor that was shown to contain CSCs, which displayed the CD44+CD24–/lo phenotype." (PMID 33763422, 2021). "In treating breast cancer, an anti-CD44 antibody-conjugated gold nanorod has been used to target and ablate CD44 positive cells." (PMID 34307351, 2021). "The CD44 is expressed on the surface of highly metastatic breast cancer cells as a co-receptor for a broad diversity of extracellular matrix ligands, primarily HA." (PMID 34770956, 2021). "In breast cancer cells, miR-143 inhibited the progression and stemness features by directly targeting CD44 3′-UTR." (PMID 34944493, 2021). "A high expression of the cell surface marker and HA receptor CD44 combined with a low expression of CD24 (CD44+/CD24−/low) marks a breast cancer cell population with a CSC phenotype." (PMID 34070901, 2021). "(C) Metastasis rates in patients with different molecular subtypes of breast cancer after they were stratified into high (≥19.5%) or low frequency of CD44-/CD24- cells." (PMID 34318746, 2021). "The combination of CD104 and CD44 markers have been used in basal breast cancer cells to identify epithelial (E) (CD104+CD44low), Hybrid E/M (CD104+CD44high) and mesenchymal (xM) (CD104-CD44high) cell populations." (PMID 34407150, 2021). "As another cell surface glycoprotein and specific receptor to hyaluronan, CD44 plays a key role in breast cancer adhesion, motion, migration and invasion, all of which have a significant impact on early tumor metastasis." (PMID 34944829, 2021). "The drug-resistant breast cancer cell lines MCF-7/ADR cells showed enhanced cellular uptake of HPPDC nanoparticles by CD44/HA-specific endocytosis." (PMID 34960948, 2021). "Taking adjacent tissues as a control, immunohistochemical results showed that breast cancer tissues had significantly high expression of CD44 and significantly low expression of CD24." (PMID 34789199, 2021). "In terms of breast cancer, when CD44 was knocked down in a CD44+/CD24− breast cancer cell subpopulation, BCSCs differentiated into non-BCSCs with low tumor potential and altered the cell cycle and expression profiles of some stem cell-related genes." (PMID 35004281, 2021). "Sorcin silencing in the breast cancer cells decreases the pool of CD44+/CD24– and ALDH1 high CSCs in vitro." (PMID 34869449, 2021). "Pearson correlation analysis showed a positive correlation of the expression of circHIF1A and CD44 in breast cancer specimens." (PMID 34120145, 2021).
breast carcinoma (continued). "Within breast cancer, the acquisition of tumor stem cell-like features, the formation of tumor spheres and the appearance of a breast cancer stem cell-specific phenotype (CD44+/CD24-) were all promoted by the occurrence of EMT." (PMID 34150623, 2021). "In this study, serum‐free suspension culture was used to identify CD44+CD24− breast cancer stem cells with high tumorigenic ability through enhanced expression of tumour stem cell markers, such as ALDH1A1, C‐Myc, OCT4, NANOG, KLF 4 and SOX2." (PMID 33305893, 2021). "CD44+/CD24- breast CSCs are crucial for the prognosis of breast cancer, but the potential prognostic values of CD44-/CD24- breast cancer cells are rarely studied." (PMID 34318746, 2021). "Previous papers have indicated that highly migratory breast cancer cells express higher levels of CD44 antigen, which is a cell-surface glycoprotein involved in tumor cell migration, and is a receptor for HA." (PMID 34770956, 2021). "The expression levels of CD44, N-cadherin, and β-catenin in breast cancer tissues were higher than those in adjacent tissues (P<0.05)." (PMID 34932597, 2021). "The anti-CD44 antibody RG7356 have shown also the possibility to activate the immune system by initiating phagocytosis through macrophage recruitment in breast cancer model." (PMID 33889547, 2021). "The expression of both proteins showed a highly correlative expression, supporting the previously published data on a direct interaction between CD74 and CD44 in breast cancer." (PMID 34209696, 2021). "The cell lines were isolated based on their expression of CD44low/EpCAMhigh or CD44high/EpCAMhigh to examine the role of CD44 in breast cancer across the various metastatic niches." (PMID 34579762, 2021). "The metabolic switch to glycolysis was demonstrated in CD44+CD24lowEPCAM+ CSCs in breast cancer, radioresistant CSCs in nasopharyngeal carcinoma, and CD133+CD49f+ CSCs in hepatocellular carcinoma." (PMID 34322664, 2021). "Treating T47D breast cancer cells with progesterone resulted in a decrease in miR-141 expression levels, which is concurrent with an increase in CD44 expression and ability to form spheres." (PMID 33916548, 2021). "It was shown that a high ratio of cells expressing CD44 to CD24 was correlated with strong tumorigenicity of breast cancer and ALDH was correlated with the metastatic capacity of the tumour." (PMID 34208799, 2021). "Unsurprisingly, CD44 is aberrantly upregulated among diverse tumors, including pancreatic cancer, breast cancer, prostate cancer, head and neck squamous cell carcinoma, and gastrointestinal cancer." (PMID 35187044, 2021). "It has been shown that inhibitors of this signalling pathway, such as quercetin and BEZ235 (dactolisib), decreased breast cancer ‘stemness’ via decreased expression of CD44+/CD24− phenotype." (PMID 34208799, 2021). "A direct link between CSC generation and bivalency was demonstrated in breast cancer where CSCs marked by high CD44 expression were generated from CD44‐low cells by TGFβ stimulation." (PMID 33197277, 2021). "Evidence supports that radiation increases phosphorylated AKT1 and AKT2 in the breast cancer MCF7 mammospheres CD44+/CD24−/low-expressing cells, whereas the inhibition of the AKT signaling pathway sensitizes MCF7 mammosphere cells to ionizing radiation." (PMID 34217266, 2021). "For other organs, comparable results were observed in the liver and spleen; a stronger fluorescence was observed in the lungs for HA-BNPs@Ptx, probably suggesting a higher CD44 expression in the lungs of the breast cancer model." (PMID 34867360, 2021). "(F) Kaplan–Meier analysis of the DFS in the testing group of luminal breast cancer patients with endocrine therapy after they were stratified into ≥19.5% of CD44-/CD24- (n = 22) vs. <19.5% of CD44-/CD24- tumor cells (n = 19)." (PMID 34318746, 2021).
breast carcinoma (continued). "In breast cancer cells with CD44+ phenotype, genes that are involved in cell motility and angiogenesis were highly expressed, and the cells were more mesenchymal, motile and predominately oestrogen receptor-negative." (PMID 34208799, 2021). "In the current study, we isolated the CD44+CD24− subpopulation cells from breast cancer (BC) cells and BC tumors, and confirmed that lnc030, a novel lncRNA, plays a pivotal role in the self‐renewal and maintenance of BCSCs." (PMID 33511005, 2021). "miR-34a inhibits breast cancer stemness and increases the chemosensitivity to doxorubicin and paclitaxel partially by downregulating the Notch1 pathway, with reduced CD44+/CD24– BCSCs and CSC marker ALDH1." (PMID 33763422, 2021). "MMP-14, a member of the MMPs family, has been shown to cleave CD44 to promote migration of osteosarcoma, pancreatic and breast cancer cells." (PMID 34944493, 2021). "A negative correlation was observed between the expression of miR-580 and CD44 in breast cancer specimens." (PMID 34120145, 2021). "For TNBC, CD44, FDFT1, G6PD, and GLS2 were significantly associated with breast cancer grade (all p < 0.05)." (PMID 35154262, 2021). "In this study, we elucidated the function of MARCH8 in cell survival, tumorigenesis, and metastasis in breast cancer, in which CD44 and STAT3 are known to contribute to the phenotypic functions mediated by cancer stem cells." (PMID 34067416, 2021). "MMP-2, together with MMP-9, participated in breast cancer cell invasion through their connection with CD44." (PMID 34944493, 2021). "In this study, we investigated this process, and found that highly migratory breast cancer cells express higher levels of the CD44 antigen, which is a cell-surface glycoprotein involved in tumor cell migration." (PMID 34770956, 2021). "Collectively, these data confirmed that breast cancer cells expressing CD44+CD24− phenotype have enhanced invasive properties." (PMID 33257841, 2021). "Taken together, our results demonstrate that STAT3 and CD44 are newly discovered targets of MARCH8 in breast cancer which can regulate cell survival and metastasis." (PMID 34067416, 2021). "The supplementation of media with LIF for 2 weeks leads to cell-state changes from MCF7 and MDA-MB-231 to CD24−/CD44+ breast cancer stem cells." (PMID 34947829, 2021). "Since the first identification of CSCs/CICs in breast cancer used a CD44/CD24 marker, CICs have been identified in a variety of solid tumors, including colon carcinomas." (PMID 33451103, 2021). "We found that 5-mRNA prognostic signature was also significantly associated with some stemness markers in other tumors (stemness marker of breast cancer and pancreatic cancer: CD44/CD24)." (PMID 34805163, 2021). "Recently, the cancer stem cell theory has proposed that CD44 can be employed as a marker of breast cancer stem cells." (PMID 34959321, 2021). "Further, the aggregation seemed to be mediated by intercellular homophilic interactions of CD44, a classic CSC marker that is strongly associated with TMEM density in breast cancer patients." (PMID 34911937, 2021). "Based on immunohistochemistry analysis of CD24 and CD44 expression in 50 breast cancer patients, Idowu MO also suggested that CD24-CD44+ BCSCs played a significant role in triple negative subtype of breast cancer." (PMID 34801088, 2021). "The knock-down of DLL1 reduces the expression of CD24 and CD44, which is the biomarker of breast cancer CSCs, and down-regulates both tumor growth and lung metastasis of luminal breast cancer." (PMID 34098945, 2021). "Our findings are in agreement with previous studies, showing that the presence of HER2-positive CTCs co-expressing a breast cancer stem cell profile (HER2+/CD44+/CD24(low)) and elevated ALDH1 activity is related to aggressiveness and radioresistance." (PMID 33799422, 2021). "Increased fraction of CD44+, CD24- CSC and Mucin-1 expression was also reported in breast cancer MCF-7 cells when exposed to tumor associated macrophages." (PMID 33889547, 2021).